PROSER2 (proline and serine rich 2)
Synonyms: C10orf47; MGC35403
Tractability: PROTAC: ubiquitination databases record sites on it; its protein half-life has been measured.
Gene: Protein-coding gene on chromosome 10 (11,823,339 to 11,872,277, forward strand). Ensembl gene ENSG00000148426.
Subcellular location (Human Protein Atlas): Cytosol; Plasma membrane
Gene Ontology:
Molecular function: protein binding
Genetic constraint (gnomAD): Loss-of-function variants: 19 observed, 14.7 expected, observed/expected ratio (o/e) 1.29, 90% interval 0.9 to 1.82. The synonymous counts are far from expectation, so gnomAD's model fits this gene poorly and the ratio says little. Missense variants: 823 observed, 529.82 expected, observed/expected ratio (o/e) 1.55, 90% interval 1.47 to 1.64. Synonymous variants: 367 observed, 237.1 expected, observed/expected ratio (o/e) 1.55, 90% interval 1.42 to 1.69.
Homologues: Orthologues: chimpanzee PROSER2 (98% identical), macaque PROSER2 (94% identical), guinea pig PROSER2 (62% identical), mouse Proser2 (62% identical), rabbit PROSER2 (61% identical), rat Proser2 (61% identical), dog PROSER2 (60% identical), pig PROSER2 (58% identical), tropical clawed frog proser2 (36% identical). Paralogues in human: TMEM143 (12% identical).
Diseases named in the same sentence as PROSER2 in open-access papers:
PROSER2 is named in the same sentence as 6 diseases in open-access papers, as found by Europe PMC text mining. Sharing a sentence is not in itself a finding about the gene and the disease. The quoted sentences say what the papers report.
osteosarcoma (3 papers, 2020 to 2024). A usually aggressive malignant bone-forming mesenchymal neoplasm, predominantly affecting adolescents and young adults. "Recently, it has been found that the risk model composed of CD180, MYC, PROSER2, and FATE1 has a great fitting effect on the overall lifetime of osteosarcoma." (PMID 34488541, 2021). "Among them, five genes, including CD180, MYC, PROSER2, DNAI1, and FATE1, with significant contribution to the model were selected as the candidate genes in the optimal prognostic risk model of osteosarcoma." (PMID 33082842, 2020).
pancreatic cancer (1 paper, 2024). "Higher expression of PROSER2 isassociated with decreased survival rates in pancreatic cancer patients,according to the Human Protein Atlas." (PMID 38293943, 2024). "We evaluated the expression of PROSER2 in pancreatic cancercell lines and patient-derived orthotopic xenograft cells (PDOXc).Furthermore, its role as a regulator inhibiting the growth and invasionof pancreatic cancer cells was elucidated." (PMID 38293943, 2024). "Furthermore, it suggested that PROSER2 may inhibit the growthand metastasis of pancreatic cancer cells and regulate its mechanismthrough binding with STK25 and the PDCD10 complex." (PMID 38293943, 2024).
cancer (3 papers, 2020 to 2025). A tumor composed of atypical neoplastic, often pleomorphic cells that invade other tissues. "PROSER2 overexpressionsignificantly reduced the metastatic ability of cancer cells, whereasits suppression had the opposite effect." (PMID 38293943, 2024). "In addition to DNAI1, another three genes, MYC, PROSER2, and FATE1, have been reported to be associated with several cancers." (PMID 33082842, 2020). "The effectors of migration and apoptosis in other cancers and developing tissues were differentially expressed: LCP1 and CXCL5 were upregulated, while PROSER2 and PCDHA6 were downregulated." (PMID 40323130, 2025).
tumor (1 paper, 2024). "Theexpression of PROSER2 in cell lines and PDOXc was detected todetermine its association with tumor progression." (PMID 38293943, 2024). "The results of proteomicanalysis showed that the expression ofproteins related to tumor progression was reduced by PROSER2." (PMID 38293943, 2024). "These resultswarrant the need for investigating the mechanism of action of PROSER2.For instance, proteins such as CCN1, the expression of which was decreasedin PROSER2-expressing cells, may be involved in promoting cell migrationand tumor vascularization." (PMID 38293943, 2024).
PROSER2 also shares sentences with these, for which no sentence is quoted: melanoma (1 paper); triple-negative breast carcinoma (1).